HOTAIR (HOX transcript antisense RNA)
Diseases named in the same sentence as HOTAIR in open-access papers (continued):
Sharing a sentence is not in itself a finding about the gene and the disease.
hepatic (3 papers, 2022 to 2024). "Furthermore, HOTAIR has the potential to be a helpful diagnostic marker for distinguishing HCC from hepatitis and LC groups." (PMID 39128100, 2024). "In conclusion, we validated that the expression of serum HOTAIR is higher in HCC patients compared to hepatitis and LC patients." (PMID 39128100, 2024). "Serum HOTAIR levels were higher in HCC patients compared to hepatitis (P = .003) and LC patients (P = .048)." (PMID 39128100, 2024). "The HOTAIR levels in serum were significantly higher in HCC patients compared to those with hepatitis (P = .003) and LC patients (P = .048)." (PMID 39128100, 2024).
Hyperglycemia (3 papers, 2022 to 2025). An increased concentration of glucose in the blood. "Hyperglycemia also links HOTAIR to injury; in HK-2 cells, HOTAIR drives apoptosis via the miR-126-5p/AKT pathway." (PMID 41303683, 2025). "In another study, the high level of HOTAIR was induced by hyperglycemia and promoted retinal angiogenesis; increased HOTAIR expression was found in the vitreous humor of patients with proliferative diabetic retinopathy." (PMID 36361470, 2022).
Hypertension (3 papers, 2020 to 2024). The presence of chronic increased pressure in the systemic arterial system. "For the first time, the findings presented here suggest that the NEAT1, HOTAIR, and GAS5 are novel diagnostic and prognostic markers for stroke associated with hypertension." (PMID 36439973, 2023). "LncRNAs NEAT1, GAS5, and HOTAIR have previously been linked to the risk and development of CVS, and to pathologic vasculature remodeling in response to hypertension, which is the primary risk factor for cerebrovascular dysfunction." (PMID 36439973, 2023). "HOTAIR was discovered to control the development of preeclampsia by inhibiting miR-106 in hypertensive diseases and vascular remodeling." (PMID 36439973, 2023). "ROC curve analysis for the NEAT1, HOTAIR, and GAS5 revealed statistically significant differences in CVS patients, whether they had hypertension or not, when compared to controls, with fair sensitivity and high specificity, implying their diagnostic values." (PMID 36439973, 2023).
kidney cancer (3 papers, 2017 to 2024). Primary or metastatic malignant neoplasm involving the kidney. "All these results showed that HOTAIR could increase kidney cancer cell migration and invasion in vitro." (PMID 28177890, 2017).
liver diseases (3 papers, 2020 to 2024). "Interestingly, various lncRNAs, such as H19, HOTAIR, and MALAT-1, and their association with liver diseases have been highlighted as potential markers for disease progression or prognosis." (PMID 32157157, 2020).
malignant glioma (3 papers, 2018 to 2022). A grade III or grade IV glioma arising from the central nervous system. "Herein, our data indicate that the lncRNA HOTAIR promotes NF-κB activity in malignant glioma cells, whereas its overexpression leads to aberrant NF-κB activation even without inflammatory stimulation." (PMID 34887871, 2021). "Taken together, our findings establish HOTAIR as a clinically-relevant biomarker of prognosis in malignant glioma patients." (PMID 29644006, 2018).
Myocardial fibrosis (3 papers, 2022 to 2024). "Previous studies reported that HOTAIR regulates the collagen-containing extracellular matrix through URI1 activation of the Wnt pathway in myocardial fibrosis." (PMID 35845040, 2022). "HOTAIR was also shown to promote myocardial fibrosis through Wnt signaling." (PMID 38132140, 2023). "However, the role of HOTAIR in MI is still evolving and a recent finding demonstrates that HOTAIR induces myocardial fibrosis through competitive binding with miR-124." (PMID 38132140, 2023).
Papillary Thyroid Cancer (3 papers, 2019 to 2024). "Furthermore, there is higher expression of HOTAIR in female papillary thyroid carcinoma tissues because of a specific genetic polymorphism of this gene." (PMID 30873206, 2019). "HOTAIR as a long non-coding RNA has been shown to be highly expressed in papillary thyroid cancer tissues with only a limited understanding of its functional roles and downstream regulatory mechanisms in papillary thyroid cancer cells." (PMID 36494673, 2022).
renal fibrosis (3 papers, 2019 to 2020). A final common manifestation of a wide variety of chronic kidney diseases characterized by glomerulosclerosis and tubulointerstitial fibrosis. "Recently, two studies have demonstrated that HOTAIR is upregulated in renal fibrosis." (PMID 31018516, 2019). "Several lncRNAs, such as MEG3, H19 and HOTAIR, were reported to play important roles in mediating TGF-β and renal fibrosis." (PMID 32203053, 2020). "Moreover, lentiviral-mediated overexpression of HOTAIR in UUO rats, led to more severe injuries, such as inflammation, necrosis and collagen deposits, an elevated score of renal fibrosis and an overexpression of fibrotic markers compared to UUO alone." (PMID 31018516, 2019).
Stroke (3 papers, 2019 to 2024). Sudden impairment of blood flow to a part of the brain due to occlusion or rupture of an artery to the brain. "Furthermore, NEAT1 and GAS5 levels were inversely correlated with stroke severity, while HOTAIR showed a positive correlation." (PMID 38920691, 2024). "Additionally, HOTAIR is involved in the regulation of neuroinflammatory responses and glial activation in the brain and could be a potential therapeutic target for multiple sclerosis and stroke." (PMID 38920691, 2024). "While most studies in the field have focused on the functional roles of long noncoding RNAs (lncRNAs) NEAT1, GAS5, and HOTAIR in CVS, less attention has been paid to their clinical relevance to stroke incidence and prognosis." (PMID 36439973, 2023). "To date, lncRNA-H19, HOTAIR, CCAT1, and MALAT1 have been widely considered to be closely related to the occurrence and development of stroke." (PMID 31934270, 2019).
synovial sarcoma (3 papers, 2021 to 2025). "A reciprocal negative regulation between HOTAIR and miR-126, associated with proliferation and migration, has also been found in synovial sarcoma." (PMID 39796183, 2025). "There is evidence that HOTAIR promotes the progression of synovial sarcoma." (PMID 36869839, 2023).
urothelial carcinoma (3 papers, 2015 to 2022). A malignant neoplasm derived from the transitional epithelium of the urinary tract (urinary bladder, ureter, urethra, or renal pelvis). "We report that HOTAIR is overexpressed in many urothelial carcinomas and the highest range of expression is associated with worse clinical parameters." (PMID 25994132, 2015). "For comparison, we instead included HOTAIR, which has been studied well in HNSCC and in urothelial carcinoma." (PMID 31412811, 2019). "In this study we therefore investigated to which extent altered expression of HOTAIR contributes to altered HOX gene expression patterns and an aggressive phenotype in urothelial carcinoma." (PMID 25994132, 2015).
urothelial cell carcinoma (3 papers, 2021 to 2022). "Urothelial cell carcinoma development and a lower overall survival rate are associated with HOTAIR SNP rs4759314 AG+GG." (PMID 36361470, 2022). "lncRNA HOTAIR was found to be an independent prognostic biomarker of overall survival for transitional cell carcinoma (TCC) patients." (PMID 35501730, 2022).
adrenocortical carcinoma (2 papers, 2020 to 2024). "Furthermore, using the GEPIA database, we found that high HOTAIR expression in adrenocortical carcinoma (ACC), COAD and KIRC was associated with shorter OS and DFS, indicating a detrimental effect of HOTAIR overexpression in these cancer types." (PMID 38696320, 2024).
asthenozoospermia (2 papers, 2017 to 2022). "For example, a decreased expression of HOTAIR may reduce H4 acetylation in Nrf2 promoter and Nrf2 expression, which is closely associated with asthenozoospermia and oligoasthenozoospermia." (PMID 28881852, 2017). "Therefore, the reduction of HOTAIR and the subsequent reduction of Nrf2, which has a protective role in normal cells, enhances oxidative stress, resulting in a negative impact on sperm motility and the presence of asthenozoospermia." (PMID 36290414, 2022).
atrial fibrillation (2 papers, 2020 to 2021). A disorder characterized by an electrocardiographic finding of a supraventricular arrhythmia characterized by the replacement of consistent P waves by rapid oscillations or fibrillatory waves that vary in size, shape and timing and are accompanied by an irregular ventricular response. "The present study is aimed at investigating whether HOTAIR functions as a ceRNA to regulate the Cx43 expression in atrial fibrillation (AF) by sponging miR-613." (PMID 33294032, 2020).
atrophic gastritis (2 papers, 2020 to 2022). "The polymorphisms rs17840857 in HOTAIR and rs17694493 in ANRIL showed a tendency to be associated with atrophic gastritis." (PMID 33333725, 2020). "HOTAIR expression was analyzed in surgical paired tissue samples of patients with GC and biopsy samples from patients with atrophic gastritis and/or intestinal metaplasia (AG ± -IM), chronic nonatrophic gastritis, and controls." (PMID 35347094, 2022).
bladder transitional cell carcinoma (2 papers, 2017 to 2019). The most common morphologic subtype of urinary bladder carcinoma (over 90% of cases). "The impacts of HOTAIR rs874945 polymorphisms combined with smoking status on tumorigenesis of urothelial bladder cancer are worthy of being further addressed in our study cohort." (PMID 30813594, 2019).
cervical tumor (2 papers, 2018 to 2025). "Findings from prior studies indicate that dysregulated lncRNAs, such as HOTAIR and MALAT1, promote cervical tumor progression and metastasis." (PMID 41300873, 2025).
chronic obstructive pulmonary disease (2 papers, 2020 to 2024). A chronic and progressive lung disorder characterized by the loss of elasticity of the bronchial tree and the air sacs, destruction of the air sacs wall, thickening of the bronchial wall, and mucous accumulation in the bronchial tree. "The expression level of HOTAIR was significantly increased in patients with (chronic obstructive pulmonary disease) COPD or lung cancer, especially in patients with advanced stage of the tumor." (PMID 33072553, 2020). "For instance, in Chronic Obstructive Pulmonary Disease (COPD), HOTAIR has been found to facilitate pulmonary vascular endothelial cell apoptosis." (PMID 38250607, 2024).
congenital heart disease (2 papers, 2022 to 2023). A heart disease that is present at birth. "Additionally, HOTAIR has been linked to heart disease and heart defects." (PMID 36869839, 2023).
Disc Degeneration (2 papers, 2022 to 2025). "Additionally, lncRNAs like HOTAIR and MEG3 have been implicated in disc degeneration, with HOTAIR promoting ECM degradation and apoptosis, while MEG3 offers protective effects by inhibiting MMP expression." (PMID 40688090, 2025).
emphysema (2 papers, 2022 to 2024). "HOTAIR knockdown mice presented increased levels of Bcl-2 and decreased levels of Bax and Cleaved-caspase 3 in the lungs, which indicates that HOTAIR gene silencing prevented emphysema and pulmonary apoptosis in CS exposed mice." (PMID 36527094, 2022). "The dysregulation of HOTAIR-mediated signaling pathways, including TGF-β (transforming growth factor-β) and Wnt/β-catenin, has been implicated in the pathogenesis of COPD and the progression of emphysema." (PMID 39201688, 2024). "Because of the elevated HOTAIR mRNA level and hypermethylation of Bcl-2 in the lung tissue of emphysema subjects, we tested whether modulation of the HOTAIR mRNA level or activity ameliorates emphysema, pulmonary apoptosis and Bcl-2 promoter hypermethylation in mouse models." (PMID 36527094, 2022). "Similarly, HOTAIR expression levels have also been positively correlated with COPD severity scores and radiological evidence of emphysema and airway remodeling." (PMID 39201688, 2024). "Our results showed that HOTAIR mRNA levels were significantly up-regulated in the HPVEC of patients with COPD, and HOTAIR down-expression can attenuate CSE-induced cell apoptosis and emphysema via DNMT1 mediated hypermethylation of Bcl-2 promoter in mice." (PMID 36527094, 2022).
intervertebral disc degeneration (2 papers, 2022 to 2023). "HOTAIR/miR-34a-5p/Notch1 signaling pathway may regulate the development of intervertebral disc degeneration." (PMID 35626352, 2022).
lung squamous cell carcinoma (2 papers, 2020 to 2023). "Increased HOTAIR gene expression levels have been identified as a diagnostic marker in patients with LA and lung squamous cell carcinoma in studies conducted with tumor tissue, plasma, and cell lines to determine the role of HOTAIR in NSCLC development." (PMID 37424727, 2023).
lymph node tumor (2 papers, 2013 to 2015). "Consistent with the observations from the ISH, the enhanced expression levels of HOTAIR correlated with a higher tumor burden, more advanced clinical staging, increased lymph node tumor burden and poor differentiation." (PMID 23717443, 2013). "HOTAIR is upregulated in cases of NPC at more advanced clinical stage and with increased lymph node tumor burden." (PMID 26448942, 2015). "Additionally, the expression levels of HOTAIR were upregulated in samples from patients with higher tumor burdens, who were defined as those with larger tumors, advanced clinical staging, increased lymph node tumor burdens and the presence of distant metastases." (PMID 23717443, 2013).
metastatic carcinoma (2 papers, 2012 to 2015). A carcinoma which has spread from the original site of growth to another anatomic site. "Further analysis performed by the same group showed that HOTAIR was also increased in the metastatic carcinomas when compared in matched primary and metastatic cancers." (PMID 25739705, 2015). "In matched primary and metastatic cancers, both HOTAIR and EZH2 had increased expression in the metastatic carcinomas." (PMID 23133536, 2012). "Thus, the data support increased expression of both EZH2 and HOTAIR in the metastatic cancers, compared to primary carcinoma." (PMID 23133536, 2012). "However, upon comparing pairs of primary versus metastatic carcinoma, both HOTAIR and EZH2 expressions more often had equivalent (31% and 52%, respectively) or increased expression (52% and 40%, respectively) in the metastasis compared to the primary carcinoma." (PMID 23133536, 2012).
multiple sclerosis (2 papers, 2023 to 2024). A progressive autoimmune disorder affecting the central nervous system resulting in demyelination. "HOTAIR, previously known mainly for its oncogenic functions, is an lncRNA that more recently has been implicated in the pathogenesis of diseases other than cancer, including multiple sclerosis." (PMID 38475720, 2024).
ovarian serous cystadenocarcinoma (2 papers, 2020 to 2025). A malignant serous cystic epithelial neoplasm arising from the ovary. "Scatter plots show the correlations between FAM171A2 mRNA expression and six lncRNAs (BACE1-AS, GAS5, HOTAIR, HOXA10-AS, PVT1, and UCA1) in ovarian serous cystadenocarcinoma samples (n = 379) from the ENCORI database." (PMID 41303609, 2025).
pulmonary arterial hypertension (2 papers, 2018 to 2024). Pulmonary arterial hypertension (PAH) is a group of diseases characterized by mean pulmonary artery pressure >20 mmHg and elevated pulmonary arterial resistance leading to right heart failure. "Conversely, the lncRNA HOTAIR was upregulated in ASD patients, with a higher upregulation noted in those progressing to pulmonary arterial hypertension, suggesting a correlation with disease severity." (PMID 39172906, 2024).
rectal cancer (2 papers, 2022 to 2026). A primary or metastatic malignant neoplasm that affects the rectum. "The expression levels of the onco-lncRNAs, including CCAT1, LOC152578, UCA1, CRNDE, PVT1, MALAT1, XLOC_000303, XLOC_006844, BCAR4, and HOTAIR, were significantly increased in the rectal cancer patients compared to the control group." (PMID 35654932, 2022).
tongue squamous cell carcinoma (2 papers, 2016 to 2021). A squamous cell carcinoma that arises from the tongue. "STEAP3-AS1 is less well understood than HOTAIR or SOX21-AS1, and it has only been reported to be associated with a poor OS in tongue squamous cell carcinoma." (PMID 33747903, 2021).
alcoholic hepatitis (1 paper, 2025). Acute hepatitis resulting from ingestion of alcohol. "In addition, other studies have shown that the long-chain non-coding RNA HOTAIR may regulate the proliferation of hepatic stellate cells by regulating the miR-148a-3p/S1PR1 axis, thereby alleviating the liver damage caused by alcoholic hepatitis." (PMID 40649881, 2025). "Ethanol can affect the biological activity of extracellular vesicles in the endothelial cells by regulating the expression of lncRNA (especially HOTAIR and MALAT1), thus affecting the inflammatory symptoms of alcoholic hepatitis." (PMID 40649881, 2025).
Angelman syndrome (1 paper, 2019). A neurogenetic disorder characterized by severe intellectual deficit and distinct facial dysmorphic features. "Previous studies have demonstrated that the invasion and migration ability of CRC cells can be inhibited by the down-regulation of lncRNA Angelman syndrome chromosome region (ANCR), HOTAIR, and transcription factor 7 (TCF7)." (PMID 31693738, 2019).
aortic valve calcification (1 paper, 2014). "In addition to stretch-mediated repression of HOTAIR that appears to occur in BAVs, it is possible that SNPs and mutations in the HOTAIR locus could be associated with aortic valve calcification." (PMID 24788418, 2014). "Additionally, further study is required to examine if perturbation of HOTAIR is sufficient to induce aortic valve calcification in vivo." (PMID 24788418, 2014).
autism (1 paper, 2025). Persistent deficits in social interaction and communication and interaction as well as a markedly restricted repertoire of activity and interest as well as repetitive patterns of behavior. "In line with that, certain RNA molecules such as the LINC00461, the HOTAIR, the hsa-miR-151a-3p, and the SNORD116 have been consistently shown to be associated with specific neurodevelopmental conditions, including autism, ADHD, and Prader-Willi syndrome." (PMID 40868063, 2025).
basal cell carcinoma (1 paper, 2023). A carcinoma involving the basal cells. "IPA identified several pathways implicated in cell proliferation and cancer biological processes, such as HOTAIR Regulatory Pathway, MSP-RON Signaling In Cancer Cells Pathway, Basal Cell Carcinoma Signaling, FAK Signaling, 14-3-3-mediated Signaling, and ERBB Signaling." (PMID 37513116, 2023).
benign breast diseases (1 paper, 2022). "In the current study, MALAT1 was down-regulated but SNCG and HOTAIR were significantly up-regulated in patients with benign breast diseases." (PMID 36376369, 2022). "In patients with benign breast disease, BCO40587 expression was positively correlated with BDNF (r = 0.67, P = 0.0003), HOTAIR (r = 0.6, P = 0.0019), CCAT2 (r = 0.52, P = 0.009), and PVT1 (r = 0.42, P = 0.44) expressions." (PMID 36376369, 2022).
benign pancreatic tumour (1 paper, 2016). "And H19, HOTAIR, HOTTIP, MALAT1, and PVT1 levels did not significantly differ between NPT and benign pancreatic tumours (BPT) tissues (p values were 0.522, 0.759, 0.200, 0.631, and 1.000, respectively)." (PMID 27028998, 2016).
Cachexia (1 paper, 2022). Severe weight loss, wasting of muscle, loss of appetite, and general debility related to a chronic disease. "To date, there have been no investigations into the role of HOTAIR and the signaling pathway involved in cancer-induced or chemotherapy-induced cachexia." (PMID 36471329, 2022).